BRAF (B-Raf proto-oncogene, serine/threonine kinase)
Diseases named in the same sentence as BRAF in open-access papers (continued):
Sharing a sentence is not in itself a finding about the gene and the disease.
thyroid cancer (continued). "A similar bypass mechanism of BRAF inhibition is also reported in thyroid cancer cells, through reactivation of HER2/HER3 signaling." (PMID 29061943, 2015). "More well-controlled studies are needed to clarify the potential links between iodine intake and molecular alterations such as mutations of the BRAF and RAS genes and BRAF and RET rearrangements in thyroid cancer." (PMID 26146517, 2015). "In fact, NFkB pathway signaling is directly activated by a T1799A mutation in the BRAF oncogene, inducing the secretion of IL8 to increase tumor aggressiveness in thyroid cancer cells." (PMID 26536459, 2015). "In thyroid cancer, induction of the BRAF oncogene leads to overexpression of miR-17-92 cluster components, with a clear shift of miR-19a/b levels to overcome miR-92a." (PMID 26442266, 2015). "The BRAF- and multi-kinase inhibitor, sorafenib, has already shown antitumor effects in thyroid carcinoma patients in a phase III clinical trial." (PMID 25879531, 2015). "The ERK kinase inhibition we observed and that has been described by others in thyroid carcinoma cells can easily be explained by inhibition of receptor tyrosine kinases or the RAF1 or BRAF molecule in the RAF-MEK-ERK kinase cascade." (PMID 25879531, 2015). "The BRAF V600E mutation causes impaired expression of sodium iodide symporter (NIS) and radioiodine refractoriness of thyroid cancer, but the underlying mechanism remains undefined." (PMID 24243688, 2014). "Sorafenib is a tyrosine kinase inhibitor being used in advanced iodine-refractory thyroid cancer and is known to inhibit BRAF kinase phosphorylation in the MAPK pathway; of note is the fact that sorafenib also inhibits CMV replication." (PMID 24559116, 2014). "In thyroid cancer, the mutant genes such as BRAF and RAS constitutively activate aberrant cell signaling pathways that control apoptosis through MAPKs signaling." (PMID 25393982, 2014). "To confirm that this is the case in human thyroid cancer cells, we used human thyroid cancer cell line BCPAP to test the role of BRAF/MAPK pathway in modulating histone acetylation of human NIS promoter." (PMID 24243688, 2014). "We previously demonstrated that FGD1 was normally maintained, hypomethylated and overexpressed by BRAF (V600E) in thyroid cancer cells." (PMID 24137342, 2013). "In this study we used murine models of BRAF-induced PTCs/PDTCs to examine the role of TAMs in thyroid cancer progression." (PMID 23372702, 2013). "We previously revealed that FGD1 was normally maintained, hypomethylated and overexpressed by BRAF (V600E) in thyroid cancer cells and in turn observed that it was hyper-methylated after ShRNA-mediated knockdown of BRAF (V600E) in thyroid cancer cell lines." (PMID 24137342, 2013). "In addition, in PTC, the BRAF mutation is intimately associated with extra-thyroidean extension, lymph node metastasis and advanced tumor stages, which are the main clinicopathological risk factors conventionally associated with the increase of recurrence and mortality rates for thyroid cancer." (PMID 23946802, 2013). "Taking these facts into consideration, the results of this study allow us to conclude that low expression of MLH1 is associated with BRAF V600E mutations and RET/PTC rearrangements and transitions (IDH1 and NRAS) in patients with thyroid carcinoma." (PMID 23414134, 2013). "There have been several genetic abnormalities associated with thyroid carcinoma including point mutations such as those in the RAS and BRAF genes, and chromosomal rearrangements such as RET/PTC and PAX8/PPARγ." (PMID 23717622, 2013). "The results of this study allow us to conclude that low expression of MLH1 is associated with BRAF V600E mutations, RET/PTC rearrangements and transitions (IDH1 and NRAS) in patients with thyroid carcinoma." (PMID 23414134, 2013).
thyroid cancer (continued). "The expansion of knowledge regarding genetic mutations in thyroid cancers has led to the use of molecular markers as an indicator of prognosis and for the malignancy diagnosis especially in indeterminate FNA samples (BRAF, RAS, RET/PTC, and PAX8/PPARγ)." (PMID 23326756, 2012). "Dysregulation of NTRK1, BRAF, Ras, and PAX/PPARγ has also been associated with the development and progression of other thyroid cancers." (PMID 22630170, 2012). "Recently, a number of tumor-related genes were found to be aberrantly methylated in association with the MAPK pathway overactivated by BRAF mutation in human cancers, such as hMLH1 in colon cancer, and SLC5A8 in thyroid cancer." (PMID 21507233, 2011). "Sorafenib also targets signal transduction along the MAPK pathway and proliferation of tumor cells in BRAF V600E-positive thyroid cancer cell lines." (PMID 22654559, 2011). "Regarding specific mutations that constituted the panel for thyroid cancer diagnostic, RAS, BRAF, RET/PTC, and PAX8/PPARγ mutations had all a 100% positive predictive value for cancer." (PMID 22654559, 2011). "The genes, coding the signaling cascade proteins (RET, RAS, BRAF, PI3K, PTEN, AKT), are mutated or aberrantly expressed in thyroid cancer derived from follicular thyroid cell." (PMID 22654559, 2011). "Sorafenib, a multitargeted small molecule kinase inhibitor, including the VEGF receptor and BRAF kinase, has also been evaluated in patients with thyroid cancer." (PMID 21048836, 2010). "Our results in thyroid cancer cells, namely those harbouring BRAFV600Emutation showed that BRAF signalling pathway provides important proliferation signals." (PMID 19878585, 2009). "Microarray analyses of 24 thyroid carcinomas – 7 classic papillary, 8 follicular variants of papillary (fvPTC), 4 follicular (FTC) and 5 PDTC – were performed and correlated with RAS, BRAF, RET/PTC and PAX8-PPARG alterations." (PMID 19809427, 2009). "Suppression of BRAF pathway in thyroid cancer cell lines (8505C, TPC1 and C643) was achieved using RNA interference (RNAi) for BRAF and the kinase inhibitor, sorafenib." (PMID 19878585, 2009). "Our results show that BRAF plays a major role in the proliferation of thyroid carcinoma cells independently of the oncogenic activation, suggesting a role of wild-type BRAF also in RET/PTC and activated RAS signalling pathways." (PMID 19878585, 2009). "In thyroid carcinoma-derived cell lines, it was observed that inhibition of BRAF signalling by BRAF kinase inhibitors or BRAF RNAi inhibits growth, transformation and tumourigenicity of cell lines harbouring BRAFV600E mutation, without any effect on apoptosis." (PMID 19878585, 2009). "BRAF and its downstream signalling pathway represent a potential therapeutic target that is being actively studied in thyroid cancer." (PMID 17179987, 2007). "Molecular inhibition of BRAF specifically using siRNA has been shown to inhibit proliferation of several different poorly differentiated thyroid cancer cell lines, some of which express V600E BRAF." (PMID 17179987, 2007). "Because BRAF is activated through multiple mechanisms in the majority of thyroid cancers, there has been an interest in targeting BRAF for potential therapeutic benefit in patients with thyroid cancer." (PMID 17179987, 2007). "Functionally, BRAF V600E is capable of inducing thyroid cell transformation in vitro and to induce thyroid cancer in vivo in transgenic mice with thyroid-specific expression of the protein." (PMID 17179987, 2007). "In this review, data supporting a role for BRAF activation in thyroid cancer development and establishing the potential therapeutic efficacy of BRAF-targeted agents in patients with thyroid cancer will be reviewed." (PMID 17179987, 2007). "Activating mutations in the BRAF gene and constitutive signalling through RAF kinases are common events in the development of thyroid cancer." (PMID 17179987, 2007). "BRAF-targeted therapy is a promising strategy for thyroid cancer." (PMID 41862440, 2026).
thyroid cancer (continued). "Selumetinib is a strong MEK inhibitor that has shown efficacy in BRAF V600E thyroid cancer." (PMID 40943615, 2025). "MEK inhibitors have shown potential in thyroid cancer treatment by enhancing iodine uptake and retention, inducing G0/G1 cell cycle arrest through reduced MEK/ERK phosphorylation, and inhibiting the viability of cells harboring BRAF mutations." (PMID 40363930, 2025). "The correlation of MPAS with the expression of BRAF RNA in patients with thyroid cancer suggests that MAPK activation in papillary thyroid cancer may be dependent on the degree of expression of the BRAF oncogene." (PMID 40869231, 2025). "The prevalence of BRAF and RAS mutations in ATC is less than that in differentiated thyroid cancer." (PMID 40791984, 2025). "In the case of thyroid cancer, BRAF and MEK inhibitors are under study." (PMID 40977811, 2025). "PTC in SO shares mutations like BRAF, RET, and RAS with primary thyroid cancers." (PMID 39963400, 2025). "Therefore, understanding the mechanisms of BRAF inhibitor resistance in thyroid cancer is crucial for developing effective treatment strategies and improving patient outcomes." (PMID 40129883, 2025). "For radioactive iodine-refractory (RAIR) differentiated thyroid cancer, tissue-based biomarker testing to identify actionable alterations (NTRK1/3 fusions, RET fusions, and BRAF V600E mutations) is recommended, with moderate certainty evidence from the American Thyroid Association." (PMID 41595456, 2025). "However, it has been shown that there is a very low concordance in BRAF, KRAS, NRAS and TERT promoter mutations between primary or metastatic thyroid tissues and plasma ctDNAs in early stage thyroid cancer patients." (PMID 40095491, 2025). "Blocking the MAPK pathway can reverse these effects in PTC without BRAF mutation, but not in BRAF-mutant thyroid cancer due to loss of SWI/SNF subunits, rendering them insensitive to its redifferentiation effects." (PMID 40463874, 2025). "Therefore, mutations in the BRAF and RAS genes remain consistent throughout the development of thyroid cancer, from well-differentiated forms to poorly differentiated and anaplastic carcinomas, serving as early drivers of the disease." (PMID 39744583, 2025). "PTEN loss in thyroid cancer can lead to resistance to BRAF inhibitors due to the interconnected nature of the PI3K/AKT pathway, which is regulated by PTEN, and the MAPK pathway, which is driven by mutant BRAF." (PMID 40129883, 2025). "Valproic acid in combination with the Ras inhibitor farnesylthiosalicylic acid (FTS) showed synergistic antiproliferative activity against BRAF-mutant ARO thyroid cancer cells, which was accompanied by suppression of Ras, survivin, and aurora A, leading to a mitotic crisis." (PMID 39935431, 2025). "Despite significant advances, a clear consensus on the prognostic utility of secondary mutations beyond BRAF in thyroid cancer is lacking, leaving clinicians with limited guidance for integrating these markers into risk stratification frameworks." (PMID 40149275, 2025). "In cases of advanced or metastatic BRAF-mutant thyroid cancer, targeted therapies such as BRAF inhibitors (e.g., vemurafenib and dabrafenib) and MEK inhibitors (e.g., trametinib) have shown promise in clinical trials, offering a therapeutic option for patients with refractory disease." (PMID 40450370, 2025). "The importance of this pathway has been well established in thyroid cancer, where in PTCs the MAPK pathway is driven by the activation of point mutations of the BRAF and RAS genes and in the RET/PTC rearrangement, these genetic alterations being found in more than 70% of PTCs." (PMID 40722651, 2025). "Hence, the follicular variant of PTC is encountered among both BRAF and RAS mutant thyroid cancers, and BRAF mutation is occasionally detected as the single oncogenic event in FTC." (PMID 39956582, 2025). "In thyroid cancer, HIF-1α, BRAF mutation, and TSHR signaling are considered key regulators." (PMID 41301693, 2025).
thyroid cancer (continued). "A multicentric, randomized, open, phase 2 clinical trial revealed that the dabrafenib + trametinib combination was not superior in effectiveness to monotherapy with dabrafenib in patients with progressive BRAF-positive thyroid cancer refractory to radioactive iodine." (PMID 40977811, 2025). "Second, given that BRAF V600E represents a well-characterized molecular target with available selective inhibitors, we also examine the relevant clinical trials and the emergence of therapeutic strategies that are uniquely tailored to thyroid cancer." (PMID 41368991, 2025). "BRAF mutations are associated with more invasive disease and a higher risk of recurrence in patients with thyroid cancer compared to those without BRAF mutations." (PMID 40085528, 2025). "BRAF V600E mutations are more prevalent in Bethesda III nodules with cytological or architectural atypia, making this gene superior to RAS mutations in the diagnosis of thyroid cancer." (PMID 40093750, 2025). "The role of SWI/SNF disruption in thyroid cancer progression has been investigated in transgenic mice with co-mutation of SWI/SNF genes and HRAS p.G12V or BRAF p.V600E, highlighting the cooperative role of SWI/SNF in promoting loss of differentiation and tumor progression." (PMID 41175860, 2025). "Metabolic profiling indicates stage-specific reprogramming, differentiated thyroid cancers (e.g., PTC-B and FTC-R) show mutation-associated metabolic signatures (BRAF, RAS), whereas ATC favors one-carbon and pyrimidine metabolism, reflecting shifts that support rapid growth and aggressiveness." (PMID 41301693, 2025). "This scenario creates a situation in which PTEN-deficient thyroid cancer cells may activate alternative survival pathways, such as PI3K/AKT, when treated with BRAF inhibitors." (PMID 40129883, 2025). "An association between elevated TIMP1 concentrations and BRAF mutations has been found in thyroid cancer, but not in CRC29,30." (PMID 39789100, 2025). "These mutations may be primary (already present in the tumor) or secondary (acquired during treatment), thus bypassing BRAF blockade by thyroid carcinoma." (PMID 40129883, 2025). "A recent study reported that activation of the JAK/STAT signaling pathway leads to the development of resistance to BRAF inhibitors in BRAFV600E thyroid carcinoma, which makes the JAK/STAT pathway a potential target for antitumor activity and to overcome drug resistance." (PMID 40361395, 2025). "Therefore, both lung and thyroid carcinomas were concomitantly diagnosed as BRAF V600E‐positive cancers." (PMID 39950095, 2025). "The LDL receptor played an important role in the RAS/RAF/MAPK (MEK)/ERK signaling cascade, and synergy between LDL-mediated receptor uptake and BRAF may lead to a worse prognosis in thyroid cancer patients." (PMID 38589799, 2024). "These novel findings may be explained by the scarcity of thyroid cancer studies analyzing the exon 11 of the BRAF gene, as most studies focus on exon 15, where the V600E variant is located." (PMID 39420942, 2024). "Moreover, we demonstrate that NG2 knockout does not affect tumor growth in vitro and in vivo, but enhances the response of BRAF-mutant thyroid cancer cells to BRAF inhibitor." (PMID 38795180, 2024). "BRAF mutation, RAS mutation, RET/PTC rearrangement, PAX8/PPARγ rearrangement, and TERT promoter mutation, are among the major molecular indicators linked to thyroid cancer." (PMID 38501105, 2024). "Interestingly, BRAF mutations and RAS mutations have been identified and generally considered mutually exclusive in thyroid cancer, but herein we found 3 patients harboring both of them, among which, 2 of 3 patients appeared to be RAIR-DTC." (PMID 37622214, 2024). "Besides traditional treatments, including surgery, radioactive iodine, and TSH suppression, BRAF(V600E)-targeted therapy is another option for thyroid cancer patients with a poor prognosis." (PMID 39052013, 2024).
thyroid cancer (continued). "Therapeutic approaches that inhibit specific mediators, first demonstrated with selumetinib, a MAPK pathway inhibitor, and subsequently with BRAF mutation inhibitors, have demonstrated the ability to restore RAI uptake for patients with metastatic RAI-refractory thyroid cancer." (PMID 38642578, 2024). "Accordingly, BRAF alterations such as BRAF V600E play a crucial role in the ligand-independent activation of the MAPK pathway, associated with the initiation and progression of thyroid cancer." (PMID 39064466, 2024). "Thus, we propose an alternative strategy for targeting NG2 to enhance the efficacy of BRAF inhibitor in BRAF-mutant thyroid cancers." (PMID 38795180, 2024). "Similar patterns are observed in patients without the BRAF mutation, highlighting the value of thyroglobulin and calcitonin as prognostic markers for thyroid cancer patients." (PMID 39767732, 2024). "Finally, we show that combined AURKB and ERK1/2 inhibition induces apoptosis in BRAF-mutant thyroid cancer cell lines, together suggesting a potential combination therapy for BRAF-mutant thyroid cancer patients." (PMID 38521968, 2024). "Using AF of BRAF V600E mutation > 28.2% to predict the recurrence of intermediate and high risk PTC has a sensitivity of 60% and a specificity of 80%, making it a potential new indicator for predicting the risk of thyroid cancer recurrence." (PMID 38607456, 2024). "In general, the output of p-ERK is relatively high in BRAF-mutant thyroid cancer cells." (PMID 38795180, 2024). "We hypothesized that AURKB inhibition will sensitize BRAF-mutant thyroid cancer cells to inhibition of the MAPK pathway." (PMID 38521968, 2024). "Thus, this study uncovers a new mechanism in which NG2 contributes to the resistance of BRAF-mutant thyroid cancer cells to BRAF inhibitor, and provides a promising therapeutic option for BRAF-mutant thyroid cancers." (PMID 38795180, 2024). "Genetic alterations, such as BRAF, RAS, PIK3CA, and PTEN mutations, serve as the driving force behind the activation of the MAPK and PI3K/Akt pathways, which represent the fundamental mechanism in the development of thyroid cancer." (PMID 38946003, 2024). "In BRAF or RAS mutated or wildtype metastatic, RAI-resistant thyroid cancers treated with BRAF inhibitors and MEK inhibitors, re-induction of RAI uptake can only be achieved in 50–71% according to a recent systematic review of seven studies and 60–95% in another recent study." (PMID 38642578, 2024). "Besides, our data also demonstrated that NG2 knockout attenuated the rebound of p-ERK and p-AKTT308 upon BRAF inhibitor treatment in BRAF-mutant thyroid cancer cells." (PMID 38795180, 2024). "In addition, we demonstrated that, although NG2 did not affect tumor growth in vitro and in vivo, it decreased the sensitivity of BRAF-mutant thyroid cancer cells to BRAF inhibitor by regulating the activities of several major RTKs." (PMID 38795180, 2024). "Notably, compared to melanomas, mutant BRAF thyroid cancers are more refractory to BRAFi treatment as evidenced by a lower overall response rate – likely indicating an increased capacity for innate BRAFi resistance." (PMID 38622136, 2024). "Dabrafenib is another BRAF inhibitor used to treat BRAF-mutant thyroid carcinoma." (PMID 38501105, 2024). "This BRAF mutant, besides promoting cancer initiation through the enhancement of thyroid carcinoma cell growth rate and survival, drives cancer progression through the inhibition of sodium-iodide symporter expression that, in turn, determines iodine unresponsiveness." (PMID 39519020, 2024). "In addition, vitamin C ROS dependently inhibits the activity of MAPK/ERK signalling via distinct mechanisms between ATP levels in BRAF mutant and wild‐type thyroid cancer cells." (PMID 37246589, 2023).